AQP4 (aquaporin 4)
Diseases named in the same sentence as AQP4 in open-access papers (continued):
Sharing a sentence is not in itself a finding about the gene and the disease.
Hydrocephalus (continued). "In obstructive hydrocephalus and subarachnoid hemorrhage (SAH), the expression of both AQP1 and AQP4 rises, probably to speed up water transport, allowing an increase in the water content of the CSF, thus decreasing the osmotic pressure." (PMID 35715859, 2022). "Supportive of this notion that AQP4 supports and facilitates intraparenchymal fluid flow, AQP4 deletion potentiates increases in intracranial pressure (ICP) in a mouse model of hydrocephalus." (PMID 32705145, 2020). "Conversely, it was significantly upregulated in the animals that did not develop hydrocephalus AQP4−/−-NH and exhibited an apparently normal phenotype." (PMID 41226330, 2025). "Conversely, lack of Spp1 gene during the first postnatal days (P0-P11) would be a critical condition that primes the brain for the development of hydrocephalus in the absence of AQP4." (PMID 41226330, 2025). "Further analysis of AQP4 deletion in both strains of mice involving gene expression and cell regulatory processes will be necessary to understand why the obstructive hydrocephalus condition appears in CD1 animals but not in C57/BL6 mice." (PMID 41226330, 2025). "In this scenario, Spp1 would be positioned as the key gene orchestrating the amelioration of congenital hydrocephalus because it is over-expressed only in animals AQP4−/−-NH that did not develop hydrocephalus." (PMID 41226330, 2025). "Another possibility suggested is the existence of a modifier gene that primes the brain for hydrocephalus development in the absence of AQP4." (PMID 41226330, 2025). "No sporadic hydrocephalus phenotype was ever observed in heterozygous (AQP4+/−) or WT animals (AQP4+/+)." (PMID 41226330, 2025). "In the AQP4/C56BL/6 mice we did not observed hydrocephalus at any age and the ventricles in these animals were smaller than the age-matched controls in all age ranges that we observed." (PMID 38956598, 2024). "It was shown that the severity of hydrocephalus correlates with the ADC and AQP4 expression." (PMID 36920936, 2023). "However, another type of edema is present in hydrocephalus with high ICP, known as interstitial transependymal edema, which has a different origin, and the role of AQP4 still needs to be understood." (PMID 36982724, 2023). "The most likely explanation is that a major redistribution of AQP4 occurs in hydrocephalus rather than an increase in overall abundance." (PMID 36226316, 2022). "Despite the importance of AQP4 in the pathophysiology of hydrocephalus, it’s expression in human fetal life is not well-studied." (PMID 35346374, 2022). "There is no apparent explanation for why AQP4 expression differs so much between common hydrocephalus and iNPH." (PMID 36204139, 2022). "Ventriculomegaly in these mice resembles that observed in Aqp4−/− animals, which show sporadic progressive obstructive hydrocephalus with LVs and TV enlargement and aqueduct stenosis, without severe changes in FV volume and mild ependymal disorganization." (PMID 34002021, 2021). "Here we identify Kidins220 as a key determinant in the control of brain water homeostasis, ventricular enlargement and hydrocephalus pathology by molecular mechanisms that involve the unexpected expression regulation of SNX27-retromer components, which in turn controls AQP4 turnover." (PMID 34002021, 2021). "While evidence from mice lacking AQP4 expression indicates about a 10% incidence of hydrocephalus triggered by complete obstruction of the cerebral aqueduct, it is not clear why such obstructions occur." (PMID 28184993, 2017). "We have shown that the AQP4 concentration is higher in the CSF of communicating hydrocephalus infants than in the CSF of non-communicating hydrocephalus patients or controls." (PMID 23659378, 2013). "Double fluorescence staining confirmed the cell-specific expression of AQP4 and did not provide any evidence of endothelial AQP4 expression in hydrocephalus." (PMID 21054845, 2010).
Hydrocephalus (continued). "Our study addresses the genes affected in their expression due to the absence of AQP4; and from the functional experiments, we hypothesised how the genes could contribute to the onset of hydrocephalus in the progeny of the AQP4−/− (AQP4-KO/CD1) mice." (PMID 38956598, 2024). "Given the importance of AQP4 in the glymphatic system, controlling its localization may lead to improved CSF drainage and could be a potential target for treating patients with TBI, post-SAH hydrocephalus, and NPH." (PMID 39958788, 2023). "In summary, we showed that FOXJ1-Cre;CEP164fl/fl mice presenting with the communicating form of hydrocephalus still demonstrated sustained glymphatic transport and AQP4 water channel expression along the microvasculature was normal when assessed in the ventral hippocampus." (PMID 35248089, 2022). "Upregulation of AQP has been found in several types of hydrocephalus or other related diseases, for example, upregulation of AQP1 and AQP4 in SAH, suggesting that we may be able to inhibit CSF secretion and alleviate hydrocephalus by downregulating AQP symptoms." (PMID 35715859, 2022). "To confirm our immunostaining data, we evaluated samples for AQP4 mRNA expression in ependymal wall tissue (from dissected SVZ) and total coronal brain slices to see the regional and time dependent expression of AQP4 during critical periods of progression of hydrocephalus." (PMID 33897371, 2021). "Thus, our data do not suggest changed cell type expression of AQP4 in hydrocephalus, but rather changed level of the constitutive expression." (PMID 21054845, 2010). "The changes in AQP4 expression coincided with significantly increased periventricular ADC value after one and two weeks of hydrocephalus, but no direct linear correlation was found." (PMID 21054845, 2010). "In a state of subacutely acquired AQP4 dysfunction, as occurs in NMO, altered CSF reabsorption could further exacerbate hydrocephalus through a nonobstructive mechanism." (PMID 27379319, 2014).
Cognitive impairment (69 papers, 2015 to 2026). Abnormal cognition is characterized by deficits in thinking, reasoning, or remembering. "MOGAD patients demonstrated lower performance in verbal learning, memory and IPS (BRB-N SRTs and SDMT) than HC, with a cognitive impairment risk similar to AQP4+NMOSD and dsNMOSD." (PMID 41493508, 2026). "AQP4 plays a pivotal role in the degradation of Aβ and the uptake of glutamate in astrocytes, with its deficiency being strongly associated with cognitive impairments." (PMID 40016145, 2025). "Application of adeno‐associated virus to overexpress AQP4 enhanced AQP4 polarization, which augmented lymphatic function and ameliorated cognitive deficits." (PMID 41152198, 2025). "It is noteworthy that Y. Fang and coauthors revealed the existence of the Aqp4 SNP form, which was associated with the faster progression of cognitive impairment and amyloid-β in CSF of PD patients." (PMID 38338949, 2024). "Overall, AQP4 appears to be a crucial mediator in the pathophysiology of sepsis-associated encephalopathy, involved in brain edema, cognitive impairment, and potentially serving as a target for therapeutic intervention in clinical settings." (PMID 39544938, 2024). "Recent studies have shown that some variants of the Aqp4 gene single-nucleotide polymorphism (SNP) are associated with a higher risk of PD development, the appearance of cognitive impairments, PD-associated regional brain activity, and clinical phenotypes." (PMID 38338949, 2024). "For example, we reported in a limited candidate gene-association study that five naturally occurring single-nucleotide polymorphisms (SNPs) in the human AQP4 gene are associated with cognitive impairment in the setting of AD." (PMID 35473943, 2022). "Glymphatic clearance mechanisms were strongly associated with AQP4, and deletion of AQP4 in AD transgenic mice resulted in increased Aβ burden and exacerbated cognitive impairment." (PMID 34650426, 2021). "Cognitive impairment may result from diffuse cortical neuronal loss following a relapse or disruption to synaptic plasticity regulated by astrocytic AQP4 expression." (PMID 40227344, 2025). "Additionally, we examined the effects of fasudil on the expression of AQP-4, which is crucial for cognitive impairment caused by systemic inflammation." (PMID 39534317, 2024). "Moreover, studies in an animal model of AD have shown that in APP/PS1 transgenic mice, AQP4 deletion exacerbates cognitive deficits and is associated with an increase in Aβ accumulation." (PMID 38334678, 2024). "We observed an older, chronic NMOSD lesion with AQP4 loss in the hippocampal CA1/2 region of patient NMO01 who was diagnosed with mild cognitive impairment and delusions at a time when her computed tomography (CT) indicated normal brain and hippocampal volumes." (PMID 36811295, 2023). "Besides, loss of AQP4 polarization impairs the glymphatic system, a newly-discovered waste clearance system in the brain, causing toxic protein deposition and cognitive deficits." (PMID 35592320, 2022). "Cognitive impairment may be associated with aquaporin-4 antibody positive (AQP4+) NMOSD, particularly where there is prominent cerebral, corpus callosum, or thalamic involvement." (PMID 35645973, 2022). "The increase in deposition of neurotoxins in the brain, WM damage, and cognitive impairment associated with tPA deficiency in aging mice, may in part, be attributed to diminished perivascular AQP-4 and impaired glymphatic waste clearance pathways." (PMID 31440383, 2019). "Disorders associated with cognitive deficit and AQP-4 up-regulation." (PMID 27252943, 2016). "The reduction in AQP4 expression was found to exacerbate the accumulation of brain Aβ and cognitive deficits in the APPswe/PS1dE9 (APP/PS1) mice; moreover, the loss of perivascular AQP4 localization might lead to the pathological process of AD in the human population." (PMID 38430054, 2024).
Cognitive impairment (continued). "Regardless of what causes cognitive impairment, AQP4 plays a role in a common, important, and complex pathway, which means that AQP4 can be used as a broad-spectrum therapeutic target to control or even reverse a variety of complex causes of cognitive impairment or unknown cognitive disorders." (PMID 35111362, 2022). "Therefore, we determined whether genetic deletion of AQP4 in APP/PS1 mice advanced cognitive impairment was associated with more severe impairment of SYP and PSD-95." (PMID 26526066, 2015). "Of equal importance is the fact that AQP4 depolarization occurs relatively early in multiple disease models, often before measurable cognitive impairment or substantial protein accumulation." (PMID 41373689, 2025). "Experimental evidence has shown that AQP4 knockout in AD mouse models dramatically worsens amyloid accumulation and cognitive deficits." (PMID 41416659, 2025). "The mislocalization of AQP4 often occurs before the measurable accumulation of amyloid-beta or cognitive impairment." (PMID 41373689, 2025). "In AQP4 + NMOSD, this subtype is linked to physical disability, while in MS, it correlates with cognitive impairment." (PMID 40898200, 2025). "The deletion of aquaporin-4 water channels significantly enhances the accumulation of Aß plaques and cognitive impairments by inhibiting the glymphatic flow, as observed in a mouse model of AD." (PMID 38300638, 2024). "Further investigations are required to mechanistically relate glymphatic dysfunction to vascular damage, DM pathology, AQP4 deficits, and cognitive impairment." (PMID 38398003, 2024). "Zhu DD and colleagues found that AQP4 aggravates cognitive impairment in SEA by inhibiting Nav1.6-mediated astrocyte autophagy." (PMID 38802927, 2024). "This study aimed to explore the potential anti-oxidative and anti-inflammatory effects of fasudil and its role in modulating aquaporin-4 (AQP-4) to improve cognitive impairment in a systemic inflammation model induced by lipopolysaccharide (LPS)." (PMID 39534317, 2024). "Dynamic evolution of cognitive impairment and serum AQP-4 antibody titers during acute and remissive stages will also be explored." (PMID 36672071, 2023). "Glymphatic function suppression by treatment using aquaporin 4 inhibitor TGN‐020 abolished the protective effect of the GLP‐1R agonist against cognitive impairment." (PMID 37353947, 2023). "The normalization of perivascular Aqp4 mislocalization, with the addition of 5-caffeoylquinic acid, led to increased Aβ clearance and improved cognitive impairment in an APP/PS2 AD mouse model." (PMID 37762391, 2023). "It has been demonstrated that the fluid dynamics problem in the brain clearing system exists in many cognitive disorders, and the mechanism of AQP-4 in cognitive disorders has also received extensive attention." (PMID 36672071, 2023). "The aim here is to investigate the effects of AQP4 associated with SAE and reveal its underlying mechanism causing cognitive impairment." (PMID 36922751, 2023). "We describe two cases of AQP4+ NMOSD with cognitive impairment persisting over more than 6 months, where cognition improved after eculizumab was initiated." (PMID 35645973, 2022). "Abnormal expression and dysfunction of AQP4 have been observed in many kinds of cognitive disorders." (PMID 35111362, 2022). "Then, the relationship between AQP4 and common cognitive disorders will be summarized, as well as the possible mechanisms." (PMID 35111362, 2022). "AQP4 shows noteworthy changes in various cognitive disorders and is part of the pathogenesis of these diseases." (PMID 35111362, 2022). "In this regard, the presence of brain lesions at sites of high AQP4 expression, atrophy of deep grey matter structures or impairment of white and grey matter integrity have been proposed to be related to cognitive deficits in NMOSD." (PMID 35629165, 2022). "In the APP/PS1 AD mouse model, AQP4 knockout exacerbated AD mice’s cognitive deficits and other typical pathological changes." (PMID 36184623, 2022).
Cognitive impairment (continued). "We believe that the in-depth study of AQP4 will provide new ideas regarding treatment strategies for cognitive disorders." (PMID 35111362, 2022). "This review will summarize the role of AQP4 in the pathophysiological processes of several cognitive disorders as reported in recent studies." (PMID 35111362, 2022). "Collectively, the expression and mechanism of action of AQP4 in AD almost completely explain the role of AQP4 in all cognitive disorders." (PMID 35111362, 2022). "We determined that lower circulating levels of AQP4 were related to Apoε4 and cognitive impairment in the univariate analysis." (PMID 33801197, 2021). "Our present results suggested that the change of miR-383-5p level and its regulation of target gene AQP4 was one of the potential molecular mechanisms of microgravity-induced cognitive impairment in the hippocampus." (PMID 33013433, 2020). "Accelerated cognitive decline has been reported in AQP4 deficient APP/PS1 mice and intraneuronal Aβ deposits are associated with neuron loss and cognitive deficit." (PMID 31068220, 2019). "Genetic deletion of AQP4 further exacerbated cognitive impairment in APP/PS1 mice, reflected by extended escape latency during the entire training periods." (PMID 26526066, 2015). "Additionally, the risk for cognitive impairment across all BRB-N tests was double in MOGAD compared to HC, similar to results for AQP4+NMOSD and dsNMOSD." (PMID 41493508, 2026). "Thus, AQP4 polarity is not only a key anatomical determinant of glymphatic efficacy but also a promising therapeutic target for mitigating cognitive impairment." (PMID 40822471, 2025). "The stimulator modulates AQP4 polarization, which is essential for enhancing glymphatic clearance, thus improving brain recovery from ischemic damage and reducing neurological, motor, and cognitive deficits." (PMID 39927473, 2025). "Our research shows that increasing the polarization of hypothalamic Aqp4 through mitochondrial energy supply may be an important target for moxibustion to improve cognitive impairment in APP/PS1 mice." (PMID 36819717, 2023). "The expression, effects and mechanisms of AQP4 in several cognitive disorders." (PMID 35111362, 2022). "For this reason, the mechanism of action of AQP4 in these cognitive disorders has also received abundant attention, which may lead to the development of new therapeutic strategies." (PMID 35111362, 2022). "Here, we briefly review the mechanism and role of AQP4 in several common cognitive disorders." (PMID 35111362, 2022). "Interestingly, in aged mice with cognitive deficits, 6-week voluntary exercise promotes glymphatic clearance of Aβ by regulating AQP4 polarization and improving the expression of AQP4 in the perivascular regions." (PMID 36184623, 2022). "In addition, we found lower circulating levels of AQP4 in patients with cognitive impairment in the univariate analysis." (PMID 33801197, 2021). "Neuroinflammation and depolarization of the aquaporin 4 (AQP4) water channel, known to be involved in impairment of the glymphatic system, were associated with enhanced amyloid pathology and cognitive impairment in our previous study using the same animal model of PSD." (PMID 32967251, 2020). "AQP4 deletion in a mouse AD model exacerbated Aβ deposition and cognitive impairment." (PMID 32075202, 2020). "Through multi-omics analysis, we found microgravity could promote a miR-383-5p level in the circulation, which could inhibit the expression of AQP4 in hippocampus and be relative to the potential mechanism of microgravity-induced cognitive impairment." (PMID 33013433, 2020). "Hence, few studies have tried to investigate the interplay of AQP4-IgG, which usually are a persistent disease factor, and cognitive impairment." (PMID 31258505, 2019). "The inactivation of A2ARs alleviates the disruption of AQP4 polarity, p-tau accumulation and neuronal damage post-injury and may become a new target for the prevention of cognitive impairment after TBI." (PMID 28533515, 2017).